INS (insulin)
Diseases named in the same sentence as INS in open-access papers (continued):
Sharing a sentence is not in itself a finding about the gene and the disease.
diabetes (continued). "We provide novel insights into the effects of diabetes treatments on these amino acids in insulin resistant states such as T2DM in a unique but understudied Thai population." (PMID 34830706, 2021). "Over 90% were taking oral hypoglycemic agents for diabetes treatment, while 44% of women and 63% of men were taking insulin." (PMID 34890440, 2021). "In the remaining four cases, we observed two patients who developed diabetes mellitus, which required insulin treatment, and two patients who developed pituitary alterations (secondary hypothyroidism and secondary hypocortisolism)." (PMID 34036513, 2021). "Type 1 diabetes (T1D), the immune-mediated form of diabetes, is a prototypical organ specific autoimmune disease in which T cells play a pivotal role in targeting pancreatic insulin-producing beta cells." (PMID 34868047, 2021). "There are two common forms of diabetes, type 1 diabetes, which is characterized by early onset and the inability to produce insulin, and type 2 diabetes, which is characterized by late onset and the inability to properly utilize insulin." (PMID 34945383, 2021). "Maintaining blood insulin levels is important for patients with diabetes because insulin secretion capacity declines with the development of the disease." (PMID 33916828, 2021). "Although some NCD medicines are well established—such as metformin and insulin for diabetes and antihypertensive agents to control some CVDs —so far, no agent has been approved for MAFLD." (PMID 34444990, 2021). "Diabetes mellitus, or diabetes for short, is a chronic disease that occurs either when the pancreas does not produce enough insulin or when the body cannot effectively use the insulin it produces." (PMID 34946438, 2021). "Previous studies have shown that meldonium can reduce blood glucose levels in both rodent models of diabetes (STZ injection) and insulin‐resistant models of diabetes (Zucker obese rats), as well as in humans with type 2 diabetes." (PMID 33458907, 2021). "Optimal diabetes management, especially for patients using insulin, requires frequent glucose monitoring, access to infrastructure and support networks, and willingness to adapt to circumstances as they change." (PMID 33470882, 2021). "A lower T50 value was found in patients with a higher HbA1c or higher systolic blood pressure, insulin users and patients with a longer history of diabetes." (PMID 33627317, 2021). "In type 1 diabetes mellitus, insulin production in the pancreas is impaired, whereas, in type 2 diabetes mellitus (T2DM), insulin efficiency in muscle or fat tissue is reduced." (PMID 34299620, 2021). "Folic acid supplementation effectively reduced the fasting blood glucose levels, insulin resistance index and blood insulin levels in diabetic patients, indicating its potential therapeutic value in diabetes." (PMID 34692767, 2021). "The rising prevalence of diabetes worldwide is bound to escalate the demand for recombinant insulin therapeutics, and currently, the majority of recombinant insulin therapeutics are produced from E. coli inclusion bodies." (PMID 34336550, 2021). "It is essential to perform rapid genetic testing for ABCC8/KCNJ11 in any patient diagnosed with diabetes before 6 months of age, particularly given issues regarding access to and cost of insulin in some populations." (PMID 34566892, 2021). "In this study, 24 patients with type 2 diabetes mellitus (T2DM) treated with insulin were selected to receive three intravenous infusions of stem cells from human exfoliated deciduous teeth (SHED) over the course of 6 weeks and were followed up for 12 months." (PMID 33660433, 2021). "With the development of recombinant DNA technology, human insulin was largely produced for the treatment of patients with diabetes." (PMID 34440929, 2021). "Using single cell RNA-seq and streptozotocin-induced diabetes in mice recently showed that insulin treatment restores beta cell function." (PMID 35155441, 2021).
diabetes (continued). "The two dietary regimens proved similarly effective in improving insulin resistance and fasting hyperinsulinemia, which are key pathogenetic mechanisms of diabetes progression, while enhancing β-cell function and endogenous insulin clearance." (PMID 33919503, 2021). "Within the diabetic group, the median number of years of having diabetes was 8 years since being diagnosed with diabetes (range, 5–11 years); most of them (82.5%) had HbA1C of >7%, and more than half (55%) used insulin." (PMID 34690653, 2021). "Diabetes mellitus is a metabolic disorder characterized by a relative or total insulin deficit and hyperglycemia." (PMID 34401085, 2021). "Current ADA diabetes recommendations state that patients with A1c values ≥10% should be started on insulin." (PMID 34458301, 2021). "In what concerns the Morus species, it seems like black mulberry leaves and some of their natural products are mainly proven to be effective in managing diabetes due to their antioxidant action and reported the capacity of increasing a serum insulin level." (PMID 33498684, 2021). "About 60.6% of the study sample were obese with 25.4% under insulin use and more than half reported taking diabetes medication other than insulin and hypertension medication (34.5%)." (PMID 33921201, 2021). "In Europe, dapagliflozin is also approved as an adjunct to insulin in patients with type 1 diabetes mellitus." (PMID 34068655, 2021). "Individuals with SAID most frequently had insulin treatment, particularly among those with the long-term diabetes (84.1 and 58.8%), while oral antidiabetic treatment was more frequent in the new-onset group (9.4 and 27.5%)." (PMID 34276762, 2021). "Diabetes mellitus is a heterogeneous disease characterized by hyperglycemia due to vitiated insulin secretion by the beta cells of the pancreas and/or vitiated insulin action." (PMID 34976508, 2021). "Concerns about late complications of diabetes and injection pain (injections/vein puncture—except for fingerstick glycemia measurements and insulin injections) were the most frequently reported." (PMID 34070638, 2021). "Long-term activation of the innate immune system impairs insulin secretion and action, and inflammation also contributes to macrovascular and microvascular complications of diabetes." (PMID 34798872, 2021). "Diabetes mellitus (DM) is a metabolic disease characterized by chronic hyperglycemia resulting from defects in insulin-producing cells, insulin action, or both." (PMID 34203697, 2021). "This echoes results reported in a previous study proposing that increased insulin sensitivity upon AdipoRon treatment can restore diabetes-induced decrease in renal and cardiac AdipoR1 and AdipoR2 expression to the levels present in control db/m mice." (PMID 34214600, 2021). "Diabetes mellitus is a complex syndrome, induced by the disturbance of insulin secretion or by the resistance of the peripheral cells to the action of insulin." (PMID 34684108, 2021). "Accordingly, pregnant women with a history of diabetes mellitus requiring insulin, thyroid disorders, chronic renal or heart disease, and/or a history of asthma were excluded from the study." (PMID 34360332, 2021). "The duration of diabetes in insulin‐naïve participants was shorter than that in insulin‐treated participants (7.7 ± 5.0 years vs. 11.3 ± 6.6 years)." (PMID 34277959, 2021). "The commonly used medications for the management of diabetes were metformin (85.8%), glimepiride (26.8%), and insulin (18.9%)." (PMID 35199748, 2021). "The presented device will be a valuable tool in islet and diabetes research for studying dynamic insulin secretion from individual pancreatic islets." (PMID 34055765, 2021). "In one of the largest studies (over 6500 participants) documenting the trajectories of insulin sensitivity and insulin secretion prior to the development of diabetes, insulin sensitivity exhibited a steep decline 5 years prior to the diagnosis of diabetes." (PMID 34206745, 2021).
diabetes (continued). "Noteworthy, disruptions of gap-junctional communication were found to impair synchronized beta cell responses and lead to dysregulated plasma insulin oscillations and to glucose intolerance, as observed in numerous models of obesity and diabetes mellitus." (PMID 34359828, 2021). "The development of insulin has been identified as one of the most significant events in the treatment of diabetes." (PMID 33466845, 2021). "Diabetes is a chronic metabolic disorder characterized by inappropriately elevated glucose levels as a result of impaired pancreatic β cell function and insulin resistance." (PMID 33546200, 2021). "Consistent with the protective effect against lipotoxicity, ablation of Rnf213 recovered insulin levels in Akita mouse, a diabetes model with impaired insulin production, and it improved glucose tolerance by protecting islet β cells." (PMID 34381413, 2021). "This technique will replace the lost β cell mass and restore insulin secretion capacity in individuals with diabetes." (PMID 34882233, 2021). "In diabetes surgery, gain parameters should consider not only weight and BMI but mainly the HbA1c, C peptide, fasting glycemic, levels of insulin, lipid profile, and comparable indexes." (PMID 35027968, 2021). "It is noteworthy that adiponectin enhances eNO generation and augments insulin action explaining why diabetes mellitus is ameliorated in WBKDF-HS group." (PMID 34334139, 2021). "We describe this phenomenon in an elderly female known with type 2 diabetes mellitus taking insulin and oral diabetes medications." (PMID 33628705, 2021). "In fact, a continuous beneficial effect after intensive insulin treatment was observed in participants of the DCCT trial after 10 years of follow-up in the Epidemiology of Diabetes Interventions and Complications (EDIC) trial." (PMID 33498918, 2021). "Several studies have shown that the VAI has the strongest correlation with diabetes and insulin sensitivity than other anthropometric markers (BMI, WC, and WHR)." (PMID 34993251, 2021). "That same year, Elliot Joslin stated, ‘A new race of diabetics [people with diabetes] has come upon the scene’ due to the discovery of insulin." (PMID 33483763, 2021). "T1D accounts for about 5–10% of all types of diabetes, once known as insulin-dependent or juvenile diabetes." (PMID 35002992, 2021). "Diabetes mellitus (DM), which is characterized by chronic hyperglycemia resulting from defective insulin secretion and/or insulin action, is a major growing threat to public health." (PMID 33623633, 2021). "Although we found no superior performance of machine learning over logistic regression, machine learning had higher accuracy in prediction of insulin initiation than general physicians, defined by diabetes specialists’ choice of the gold standard." (PMID 33502325, 2021). "This type of diabetes is characterized by a decreased insulin effect and a reduction in the insulin distribution and occurs more and more frequently also in younger people." (PMID 33587221, 2021). "Bifidobacterium and Lactobacillus had been reported to be poorly represented in the fecal samples of diabetes patients and positively impact insulin sensitivity." (PMID 34257649, 2021). "In diabetes, acidity affects insulin capacity to join the receptor, increasing the peripheric resistance and exacerbating symptoms." (PMID 34680546, 2021). "Diabetes is a group of metabolic disorders that are characterized by hyperglycemia which is developed for a defect in insulin production, insulin function, or both." (PMID 34255619, 2021). "Several reports also describe the inhibitory effect of H2S on glucose-stimulated insulin secretion as a factor contributing to the development of diabetes." (PMID 34266472, 2021). "T2DM patients used oral medications, insulin, or a combination of both to treat and control diabetes." (PMID 33924022, 2021).
diabetes (continued). "Self-monitoring of blood glucose (SMBG) is an integral component of therapy for patients with diabetes, with monitoring frequency differing according to diabetes type, patient therapy (insulin versus non-insulin) and patient characteristics." (PMID 34695917, 2021). "Diabetes is a complex metabolic disease in which the body’s ability to produce or respond to insulin is impaired, resulting in hyperglycemia." (PMID 34589059, 2021). "Epidemiological studies have established that plasma apoC-III levels are positively associated with diabetes, and that Apoc3/APOC3 gene transcription increases in rat and human hepatocytes under high glucose conditions and is inhibited by insulin." (PMID 33918571, 2021). "Among the major known targets affected by mitochondrial dysfunction in diabetes are insulin signaling, synthesis and secretion pathways, and insulin sensitivity/resistance in the peripheral muscle." (PMID 34201756, 2021). "Metformin, an oral anti-hyperglycemic agent, is a first-line therapy for type 2 diabetes mellitus (DM) due to an improvement of insulin sensitivity and a decrease in glucose production." (PMID 35096887, 2021). "In all cases, pregnancy complicated by diabetes involves large amounts of maternal glucose freely cross the placenta, leading to increased secretion of foetal insulin." (PMID 34680959, 2021). "While 11 (17.7%) patients in the menopausal transition group had insulin-regulated diabetes mellitus, 14 patients (14%) in the postmenopausal group were receiving insulin therapy." (PMID 35103149, 2021). "Decreased acute insulin response to intravenous glucose tolerance test (IVGTT) during first-phase insulin secretion (FPIS) is a characteristic of diabetes." (PMID 34867781, 2021). "Insulin therapy is the most effective method of lowering blood glucose, thus pharmacological agents that augment insulin release are a key part of the treatment of diabetes." (PMID 33919190, 2021). "Overnutrition rapidly induces insulin resistance in the brain, even before peripheral insulin signaling is impaired, implicating insulin resistance in the brain as a major culprit in diabetes." (PMID 35048037, 2021). "All solutions for improving access to insulin need to have people with diabetes playing a key role, both being driven by people with diabetes and being designed with people with diabetes in mind." (PMID 33483763, 2021). "We evaluated a non-HLA T1DGRS and a T2DGRS, stratified by HLA group, in our cohort of individuals with insulin-treated diabetes aged 31–50 years within UK Biobank." (PMID 34272580, 2021). "The primary goal of exercise in diabetes is to improve overall cardiovascular health, improve insulin sensitivity, and modify endothelial dysfunction produced by diabetes." (PMID 33708143, 2021). "Klotho induces insulin production and secretion in vitro and in vivo, attenuates insulin sensitivity in mice, and is depleted in pancreatic islets of type 2 diabetes mellitus (T2DM) patients." (PMID 34944918, 2021). "In the context of diabetes, these attributes include injecting insulin or testing one's blood sugars in public, dietary restrictions, and physical traits such as obesity." (PMID 34305751, 2021). "A more recent paper described 14 different diabetes self-management games that often simulate problem solving of trying to balance food, insulin, and blood glucose." (PMID 33656447, 2021). "Corroborating this idea, the inhibition of the IKKβ–nuclear factor-κB (NF-κB) pathway via pharmacological and genetic means ameliorated insulin sensitivity in mice and improved glycemic control in individuals with diabetes." (PMID 34959837, 2021). "The impact of a given genetic variant will depend on how deleterious it is for a particular mechanism controlling insulin secretion, thus determining the diabetes phenotype and the possible therapeutic interventions." (PMID 33828531, 2021).
diabetes (continued). "Differentiation of human pluripotent stem cells into insulin-producing stem cell-derived beta cells harbors great potential for research and therapy of diabetes." (PMID 34415483, 2021). "Regular standardized telephone contact with a diabetes nurse educator, including a review of blood glucose results and insulin dose adjustments, problem-solving and diabetes education." (PMID 38774890, 2021). "We obtained additional insulin from neighbouring pharmacy and diabetes clinic when the insulin was unavailable." (PMID 33884191, 2021). "Insulin has a positive effect by ameliorating the dramatic impact in bone mineral density and bone microstructure induced by diabetes mellitus." (PMID 33906655, 2021). "Clinically relevant and topical factors related to muscle wasting including sarcopenia, such as vitamin D, myostatin, insulin (related to diabetes), insulin-like growth factor I, mitochondria, and physical inactivity, are discussed." (PMID 34063269, 2021). "This type of diabetes is characterized by the irreversible destruction of over 90% of the beta-cells that produce insulin." (PMID 34944607, 2021). "Type 1 diabetes, which is known as adolescent diabetes or insulin-subordinate diabetes, is an interminable condition where the pancreas delivers mostly zero insulin." (PMID 33894739, 2021). "Pancreatic β-cells are unique in their ability to secrete insulin in response to a rise in plasma glucose, and insufficient insulin secretion from β-cells leads to the development of diabetes." (PMID 33239359, 2021). "Sixty patients with diabetes mellitus were under treatment with oral antidiabetic drugs and 6 under insulin therapy." (PMID 33672318, 2021). "Reportedly, low BMI is a strong predictor of habitual exercise; thus, low adiposity can protect ones from diabetes through exercise-induced increase in muscle insulin sensitivity." (PMID 33436978, 2021). "Type 2 DM is the most widely recognized type of diabetes where hyperglycemia occurs because of insulin resistance because of the diminishing function of the target tissue to react appropriately to insulin and dysfunctional β cells." (PMID 34497854, 2021). "The insulin deficiency requires lifelong insulin therapy and type-1 diabetes (T1DM), accounts for 5–10% of the total cases of diabetes worldwide." (PMID 34828602, 2021). "The GLP1 receptor is a potent regulator of glucose homeostasis via enhancing pancreatic secretion of insulin in a glucose-dependent manner, and several current commercial diabetes therapies have successfully exploited this." (PMID 34822370, 2021). "Diabetes mellitus (DM) is caused by chronic hyperglycemia due to impaired β-cells from the islets of Langerhans, distributed throughout the endocrine pancreas to produce appropriate insulin levels or ineffective insulin usage." (PMID 34445786, 2021). "A third concept supporting naturally occurring duct-to-beta-cell reprogramming is the presence of INS+ cells in adult pancreatic ducts, especially in diabetes and other conditions that favor beta-cell growth." (PMID 33820959, 2021). "There is a high physiological similarity, as, for example, pig insulin has been used to treat diabetes for decades." (PMID 34834962, 2021). "We therefore explored the effect of initiation of insulin therapy on body weight by taking weight change prior to initiation into account, using the available data of the Zwolle Outpatient Diabetes project Integrating Available Care (ZODIAC) cohort." (PMID 33855214, 2021). "Type 2 diabetes mellitus is characterized by both resistance to the action of insulin and defects in insulin secretion." (PMID 33986669, 2021). "Metformin, a drug used to treat type 2 diabetes, is the most widely prescribed diabetes medication worldwide because of its outstanding insulin regulatory effect, low cost, suppression of diabetes complications, and anticancer effects." (PMID 34922421, 2021).